L1CAM (L1 cell adhesion molecule)
Diseases named in the same sentence as L1CAM in open-access papers (continued):
Sharing a sentence is not in itself a finding about the gene and the disease.
tumor (continued). "This was reflected as a higher metastatic tumor burden in L1CAM high injected cells as compared to L1CAM low cells as indicated by liver/body weight ratios." (PMID 38253555, 2024). "In CRC, L1CAM has been proven to be a potential marker for tumor invasiveness, metastasis, lymph node metastasis, and worse patient outcomes." (PMID 37610689, 2024). "Inhibiting L1CAM, a neural adhesion protein in tumor ECs, results in pruning and fortification of vessels, thereby reducing tumor growth and metastases." (PMID 38580870, 2024). "SCs also communicate with tumor cells though secretory proteins, including the L1 cell adhesion molecule (L1CAM) and transforming growth factor beta (TGF-b)." (PMID 38542008, 2024). "Results of the IHC analysis revealed the upregulation of L1CAM in tumor tissues from metastatic LNs where ADAMTS1 was overexpressed and the downregulation of L1CAM in tumor tissues from metastatic LNs where ADAMTS1 was knocked down." (PMID 38263290, 2024). "We also evaluated the spatial distribution of the two HOT cellular populations within individual HOT tumor by examining the distribution of the L1CAM and LINC01187 expression in a single HOT tissue section through dual RNA-ISH staining." (PMID 37994665, 2024). "In the examined classic chRCC cases, focal L1CAM expression were co-detected with LINC01187 expression in the same tumor cell." (PMID 37994665, 2024). "In line, it has been shown that the enteric neuronal network guides tumour cell migration, with tumour epithelial cells establishing direct interactions with enteric neurons via N-cadherin and L1CAM." (PMID 38957473, 2024). "Among these, the L1 cell adhesion molecule (L1CAM) has emerged as a critical prognostic marker, associated with aggressive tumor behavior and poor outcomes." (PMID 38893238, 2024). "The relationship between FOXC1 and L1CAM in TNBC was examined by investigating their protein expression levels using IHC in tumor samples from 40 TNBC patients." (PMID 38183514, 2024). "Soluble L1CAM secreted by SCs attracts tumor cells and, through the STAT3 signaling pathway, induces the production of metalloproteinases MMP2 and MMP9, which facilitate the breakdown of the extracellular matrix (ECM)." (PMID 38542008, 2024). "In eOC, L1CAM is involved in cell proliferation, invasion and migration, which is required for i.p. tumor growth and protection from apoptosis 63,64." (PMID 39431018, 2024). "The integrin αvβ3 ligand L1 cell adhesion molecule (L1-CAM) expressed on BC cells is necessary for BC metastasis to the lungs, where it allows tumor cells to combine and extravasate through the lung endothelium." (PMID 38637802, 2024). "L1CAM can also mediate tumor-nerve adhesion, allowing CRC cells to migrate along enteric neurons in vitro and potentially contributing to PNI." (PMID 37610689, 2024). "Grunewald utilized light projection-based bioprinting technology to establish a neuroblastoma model with GelMA and observed infiltration of CD8+ L1CAM-specific CAR T cells dispersing from the top to bottom of the 3D tumor models." (PMID 38520648, 2024). "Anti-tumor efficacy correlates with a reduction in a subpopulation of cancer initiating like cells (CICs) identified by their expression of L1CAM/CD133 and highest telomerase activity." (PMID 38253555, 2024). "Analysis of differential gene expression revealed the association of TLS with the overexpression of L1CAM, where mature TLS expressed this gene independently of L1CAM expression in the tumor." (PMID 39229264, 2024). "Our study has identified, in addition to systemic levels of testosterone, tumor-specific AR and its fucosylation signaling effectors (FUT4, fucosylated-L1CAM, and AJs), as potential risk factors for disease progression and as promising prognostic biomarkers." (PMID 38326303, 2024).
tumor (continued). "In brain metastases, the expression of L1CAM is increased in the interface between tumor and endothelial cells." (PMID 38255995, 2024). "Instead, only one constituent cell within the tumor labels for IC markers; the other cellular component labels faithfully and consistently for a PC cell marker, L1CAM." (PMID 37994665, 2024). "L1CAM is a cell surface glycoprotein with an extracellular portion, which plays a pro-angiogenic role in endothelial cells of tumor-related vessels." (PMID 37248458, 2023). "Disseminated tumour cells employ L1CAM to spread on capillaries and colonise the brain by mediating β1 integrin‐ and integrin‐linked kinases and thereby activating YAP and MRTF." (PMID 37830128, 2023). "GATA3 and L1CAM always exhibit diffuse and strong expression, with a recent study of PRNRP showing that GATA3 and L1CAM demonstrated more heterogeneous staining in a pattern of varied intensity (weak to strong) and extent (20% to 100% of the tumor cells)." (PMID 37924117, 2023). "For example, L1CAM promoted STAT3 activation via the IL-6/IL-6Rα axis to regulate tumor angiogenesis and vessel stabilization." (PMID 37248458, 2023). "The L1 cell adhesion molecule (L1CAM) is a trigger factor of metastasis and is upregulated in tumor that have undergone neoadjuvant chemotherapy." (PMID 37215622, 2023). "This correlation is closely related to the ability of L1CAM to enhance tumor cell proliferation and invasion and to maintain tumor stemness." (PMID 37015905, 2023). "Still, a recent publication by Ganesh and collaborators defined L1 cell adhesion molecule (L1CAM) expression as a fundamental requirement for metastatic tumor regrowth." (PMID 36168102, 2023). "Tumor-endothelial adhesion assay showed L1CAM knockdown reduced the adhesion of RCC cells to vascular endothelial cells." (PMID 37015905, 2023). "Our results suggest that L1CAM deploys the perivascular tumor niche of RCC and is involved in the malignant process of RCC cells." (PMID 37015905, 2023). "We found that the tumor‐invasion and tube‐formation capabilities of L1CAM‐overexpressing cells were significantly enhanced in vitro and in vivo." (PMID 36708044, 2023). "By secreting plasminogen activators, astroglia activate plasmin, which cleaves both Fas-ligand to destroy cancer cells and L1 cell adhesion molecule (L1-CAM) to block adhesion of the tumor cells to the vessel walls." (PMID 37749707, 2023). "Positive L1CAM sections were presented with the staining of cell membranes, especially in the tumor–stroma interface." (PMID 36387224, 2022). "Photo‐documentation of CAM tumors developing from inoculated RB cells and quantification of tumor weight and size revealed that L1CAM‐depleted RB cells develop significantly smaller tumors than control cells, exhibiting lower weight and size." (PMID 34228897, 2022). "The feature set II (FSII) adds four more variables to the FSI, namely tumor diameter > 5 cm, peritoneal washing status, ER status and CD171 expression (L1CAM, postoperative L1 cell-adhesion molecule expression status)." (PMID 36513790, 2022). "According to the established cut‐off value of >10%, 26 (47%) tumours were L1CAM positive, with 14 (54%) samples showing intense and diffuse staining in more than 50% of tumour cells." (PMID 35429348, 2022). "These two treatments were also successful in completely eradicating L1CAM positivity within the tumour region." (PMID 34910361, 2022). "Both are built on two sets of variables: a clinical set and an extended set, which enriches the former with biomarker data, namely CD171 (L1CAM, L1 cell adhesion molecule expression), estrogen receptor (ER) status, peritoneal washing and tumor size." (PMID 36513790, 2022).
tumor (continued). "Prior studies have shown that L1CAM, an essential cell adhesion molecule, is aberrantly expressed in tumor cells where it promotes cell migration and invasion." (PMID 36509990, 2022). "We showed that L1CAM is upregulated in precursor tumor cells and that it is required for sphere formation and survival under anchorage-independent conditions." (PMID 36509990, 2022). "Although GAPDH is often treated as a housekeeping gene, a regulatory analysis revealed its novel anti-tumor, anti-inflammatory action by interacting with L1CAM, an oncogenic transmembrane protein." (PMID 35804814, 2022). "Taken together these data indicate that expression of L1CAM in FTSEC is sufficient to evoke multicellular aggregation and promote anchorage independent survival, the phenotypes associated with early tumor cell dissemination from the fallopian tube." (PMID 36509990, 2022). "Another team also found that 34.9% of NSCLC patients had L1CAM-positive expression and more than half of M1 stage tumor showed L1CAM-positive expression." (PMID 35525225, 2022). "L1CAM is involved in tumor progression of several cancer entities, in which high L1CAM expression is associated with advanced tumor stages, metastases, and poor prognoses." (PMID 34228897, 2022). "The finding that L1CAM-specific antibodies were able to partly block the functions of L1CAM in vitro is consistent with animal studies showing that L1CAM-specific antibodies can block tumor progression in a peritoneal cell line xenograft model." (PMID 36509990, 2022). "We therefore strongly support future studies to evaluate L1CAM expression in tumour samples of primary and recurrent EC to further refine systemic therapy in these specific cases." (PMID 35429348, 2022). "Extending clinical variables with the ER and L1CAM status indicators, tumor diameter > 5 cm and peritoneal washing status, improves the discrimination and calibration performance in both model types." (PMID 36513790, 2022). "L1CAM blocking antibodies have already been shown to inhibit tumor cell growth in vitro and in mouse models." (PMID 34228897, 2022). "Compared with the L1CAM low expression group, the L1CAM highly-expressed group is consisted of upregulation of tumor-promoting pathways including PI3K-Akt signaling pathway, MAPK signaling pathway, cell adhesion molecules, and synapse organization." (PMID 36212450, 2022). "Vast evidence has supported the fact that the L1CAM is a major driver for tumor cell invasion and motility." (PMID 36387224, 2022). "Compared to untreated specimen, a significant reduction in L1CAM expression was observed in the chemotherapy‐treated RB tumor samples investigated." (PMID 34228897, 2022). "The Pfister EPN dataset showed a selective increase in expression of the tumor invasion-promoting L1CAM gene in the ST_EPN_RELA subtype at a very high level of significance (by Anova, F = 175, p = 1.35 × 10−81)." (PMID 36293188, 2022). "In the study presented, we analyzed known L1CAM regulating miRs in order to unravel their function in RB tumor progression and chemotherapy resistances." (PMID 34228897, 2022). "In vivo, silencing of L1CAM expression suppressed tumor growth and increased the survival of tumor-bearing animals." (PMID 35565425, 2022). "Subsequent research attests to the presence of L1CAM in several cancer cell types, and a high L1CAM expression correlates with advanced tumor stages and grave prognoses." (PMID 35473609, 2022). "L1CAM measurements were available in 47 of the 49 tumor samples, all of which demonstrated strong expression." (PMID 36142656, 2022). "L1CAM depletion induced apoptosis and reduced RB cell viability in vitro and tumor growth and migration in vivo." (PMID 34228897, 2022). "Serotonin treatment increased the NF-κB levels in tumor cells, whereas L1CAM silencing suppressed the upregulation of NF-κB." (PMID 35473609, 2022).
tumor (continued). "In the study presented, we demonstrated the effect of L1CAM on RB cells' apoptosis, proliferation, viability, growth, and colony formation capacity in vitro as well as on their tumor formation and migration capacity in vivo." (PMID 34228897, 2022). "In this case, the SC-secreted soluble L1 cell adhesion molecule (L1CAM) serves as a chemoattractant for tumour cells and leads to increased production of matrix metalloproteinase MMP-2 and MMP-9, which help in PNI process." (PMID 35269454, 2022). "Through tumor-nerve adhesion mediated by L1CAM and N-Cadherin, CRC tumor cells can migrate along enteric neurons in vitro, representing a possible route for CRC perineural invasion due to the wide distribution of enteric nerves throughout the colon and rectum." (PMID 35223829, 2022). "Reciprocally, previous studies have also indicated that inhibition of TGF-β1 signaling or L1CAM signaling abrogated these effects and likewise inhibited platelet-derived TGF-β1/L1CAM/integrin/NF-kappaB pathways induced tumor invasion metastasis cascade." (PMID 36387224, 2022). "The differences between GRIN1 and tumor mutational load (TMB) and microsatellite instability (MSI) were statistically significant, while L1CAM was negatively connected with TMB and SEMA4F was positively correlated with MSI." (PMID 36212450, 2022). "The present study confirmed the high expression of LINC01426, L1CAM, and tumor infiltration of T follicular helper cells because these cells were closely related to the clinical and prognostic prediction of KIRC." (PMID 36072969, 2022). "To further validate the effects of the anti-L1CAM antibody on tumours, we investigated the effects of Ab417 treatment and radiotherapy or Dox treatment on tumour growth in nude mice bearing metastatic breast carcinoma MDA-MB-231 xenografts." (PMID 34078883, 2021). "L1CAM has long been known as a key player in tumor cell migration and invasion in different cancer types including OC." (PMID 34645505, 2021). "Tregs produce high levels of TGF-β, which in turn further upregulates L1CAM expression in tumor cells and promotes tumor progression." (PMID 33710805, 2021). "The results demonstrated the tumor-suppressing function of L1 cell adhesion molecule (L1CAM), which contributes to stemness in EMT." (PMID 33928036, 2021). "To provide further evidence that FAS induction on the tumor cells was the mechanism responsible for enhancing the cytotoxic efficacy of L1CAM-specific CAR T cells, we conducted experiments to specifically block FAS activity." (PMID 34771652, 2021). "It is still unclear how intracellular or secreted L1CAM plays a critical role in stemness maintenance and tumor progression/metastasis of CSCs." (PMID 33897875, 2021). "Functional studies showed that L1CAM promotes several stemness-related properties in OC cells, including sphere formation, tumor initiation and chemoresistance." (PMID 34645505, 2021). "We identified three tumor suppressor miRNAs (miR-34a, miR-124, and miR-1271) that target three adhesion molecules (L1 Cell Adhesion Molecule (L1CAM), Integrin Subunit Beta 3 (ITGB3), Catenin Delta 1 (CTNND1))." (PMID 34298609, 2021). "Patients with L1CAM positive tumours showed a shorter disease-specific survival (DSS) (L1CAM continuous: HR=1.03, CI: 1.01-1.04, p<0.001; L1CAM 10% threshold: HR=4.89, CI: 1.82-13.18, p<0.001)." (PMID 34659530, 2021). "Here we show that CAR T cells targeting L1CAM with CD28 signaling more effectively control tumor growth than CAR T cell designs using 4-1BB signaling." (PMID 33801448, 2021). "In OC, L1CAM has been shown to sustain tumor aggressiveness by enhancing cell proliferation, invasion and resistance to apoptosis, and is required for intra-peritoneal tumor growth and dissemination of OC cells." (PMID 34645505, 2021).
tumor (continued). "Further, L1CAM has been shown to have a function in cancer, as it promotes the proliferation, migration, invasion, and chemoresistance of tumour cells, and its expression is correlated with poor prognosis and metastases in various cancers." (PMID 34078883, 2021). "Analogous effects were observed on tumor take, which was reduced in L1CAM-knockdown cells and increased in L1CAM-overexpressing cells." (PMID 34645505, 2021). "As such, L1CAM is enriched in the invasive front of primary tumours, matched metastases, small cell-clusters invading lymphovascular vessels, and post-therapy surgical resection samples, implicating L1CAM in both metastasis and chemoresistance." (PMID 33673710, 2021). "In this study, we found that the expression of L1CAM was higher in tumor tissues than in adjacent tissues and was correlated with tumor differentiation and tumor stage in ESCC." (PMID 33710805, 2021). "L1CAM is shown to be involved in proliferation, invasion, and metastasis of different tumor types and is engaged in homophilic interactions with many other ligands in a context-dependent manner." (PMID 35008571, 2021). "We also investigated the benefit of tailored therapy following L1CAM assessment for stratification in our interdisciplinary tumour board." (PMID 34659530, 2021). "Nevertheless, we observed apoptosis in significantly more human L1CAM-LS-CD28/ζ CAR T cells after in vitro stimulation with L1CAM-positive tumor cells compared to the short spacer design." (PMID 33801448, 2021). "On the other hand, OvCA malignant ascites-derived exosomes display a cargo of tumor progression related proteins, such as L1CAM, CD24, ADAM10, and EMMPRIN, which have been found to correlate with worse prognosis." (PMID 34768926, 2021). "To develop a therapeutic antibody with anti-tumor activity, we previously isolated a human mAb (Ab4) that specifically binds to human and rodent L1 cell adhesion molecule (L1CAM) from a human naïve Fab library using phage display." (PMID 34206616, 2021). "The Ab612 showed 2.6-fold higher productivity and improved biophysical properties, such as 1.4-fold increased purification yield, greater stability, lower aggregation propensity, 2-fold higher affinity for human L1CAM, and enhanced in vivo anti-tumor efficacy." (PMID 34206616, 2021). "To understand how Tregs induce L1CAM expression in tumor cells, we analyzed the supernatants from the Tregs or EC1 cells cultured alone, or from the EC1 and Treg co-culture system." (PMID 33710805, 2021). "In this study, we investigated how L1CAM expression in ESCC affects the oncogenic characteristics of tumor cells and the tumor microenvironment." (PMID 33710805, 2021). "Ablation of L1CAM in ESCC cells inhibited tumor growth and migration, and increased tumor cell apoptosis (P < 0.05)." (PMID 33710805, 2021). "Highest CAR T cell infiltration was detected after 24 hours, when 198,433 SS-BB/ζ L1CAM-CAR T cells and 49,823 LS-BB/ζ L1CAM-CAR T cells had infiltrated the tumor model." (PMID 34267756, 2021). "We also observed upregulation of PD1 and TIM3 immune checkpoint molecules, indicative for exhaustion, on tumor-infiltrating L1CAM-specific CAR T cells with CD28 signaling." (PMID 33801448, 2021). "In contrast, bioluminescence at the tumor site rapidly increased in all mice following L1CAM-SS-28/ζ CAR T cell injection, demonstrating efficient CAR T cell homing and expansion." (PMID 33801448, 2021). "Live-cell imaging revealed T cell proximity to tumor cells and infiltration of untransduced and L1CAM-CAR T cells into the bioprinted 3D models." (PMID 34267756, 2021). "Of note, L1CAM has been shown to mediate pericyte-like spreading of disseminated tumour cells on host tissue capillaries by activating YAP, a key common denominator of the revival stem cell signature and the regenerative response to injury." (PMID 33673710, 2021).